SPRY2 (sprouty RTK signaling antagonist 2)
Diseases named in the same sentence as SPRY2 in open-access papers (continued):
Sharing a sentence is not in itself a finding about the gene and the disease.
tumor (continued). "Overexpression of SPRY2 abolishes the inhibitory effect of co-inhibition of FGFR, EGFR, and MET on tumor growth despite reduced ERK and Akt activation, suggesting that additional mechanisms are involved in the tumorigenic potential of SPRY2 in GB." (PMID 41516252, 2025). "The S121 phosphorylation site is involved in the protein stability of SPRY2, and the inhibitory effect of SPRY2S121A on tumor growth indicates that reduced stability of SPRY2 blocks GB tumor growth." (PMID 41516252, 2025). "MiR-27a reduces SPRY2 and FOXO3 in U87 GB cells, but the inhibition of miR-27a impairs the proliferation of U87 cells and the tumor growth of U87 cells in subcutaneous mouse tumor xenografts, in which SPRY2 and FOXO3 are increased." (PMID 41516252, 2025). "This inhibitory effect of FOXO3 overexpression on tumor growth was diminished by downregulation of SPRY2, confirming the important interplay between FOXO3, miR-21, and SPRY2 in NB." (PMID 41516252, 2025). "Although the major function of SPRY2 is the inhibition of RTK signaling, it acts as an oncogene in colon cancer and in GBM, while in most other tumors, it fulfills its canonical role as tumor suppressor." (PMID 39682716, 2024). "SPRY2 has been reported to be an inhibitor of MAPK/ERK signaling, which is important for tumor growth and metastasis." (PMID 36749775, 2023). "Mechanistically, we uncovered SPRY2 interfered with SRC-LDHA interaction to inhibit LDHA phosphorylation and suppress glycolysis in tumor stroma." (PMID 37507768, 2023). "To investigate the in vivo consequence of SPRY2 knockdown in the TME, we co-injected tumor cells with shNC or shSpry2 stromal cells subcutaneously and into tail vein." (PMID 37507768, 2023). "Indeed, as Spry2 (and other Sprouty and SPRED proteins) is a potential tumor suppressor protein that is downregulated in many different tumor types, targeting S-acylation may present a viable approach to enhance Spry2 levels and restore optimal growth factor signaling." (PMID 36442513, 2023). "In BRAF or RAS mutant tumor cells, DUSP4, DUSP6, SPRY2, and SPRY4 tend to be highly expressed, allowing tumors to evade regular MAPK signaling pathway feedback." (PMID 36437939, 2022). "Conventional wisdom is that Sprouty2 (SPRY2), a suppressor of Receptor Tyrosine Kinase (RTK) signaling, functions as a tumor suppressor and is downregulated in many solid tumors." (PMID 34685612, 2021). "Of these, Sprouty2 (SPRY2) and Sprouty4 (SPRY4) are downregulated compared to the corresponding non-tumor tissues, suggesting that they act as tumor suppressors in cancer via suppressing the MAPK/ERK signaling pathway." (PMID 34204242, 2021). "Other observations have shown that the effect of miR-21 on tumor invasion can also take place by inhibiting tumor suppressor genes ANP32A, SMARCA4 and sprouty homolog 2 (Spry2)." (PMID 32349263, 2020). "In brain tumors, repression of Spry2 has been shown to interfere with proliferation of GBM-derived cell lines and tumor formation." (PMID 31374860, 2019). "Treatment of CAKI-1 and 786-O cells with a miR-122 inhibitor led to a G0/G1 arrest and overexpression of Spry2, which resulted in activation of the Ras/MAPK pathway and improved tumor cell proliferation." (PMID 29410711, 2018). "By overexpressing SPRY2‐wide type or SPRY2‐Y55F, the tyrosine‐55 of SPRY2 was demonstrated to be essential in suppressing ERK phosphorylation, tumour invasion and EMT of ICC cells." (PMID 30160357, 2018). "Moreover, SPRY2 was significantly correlated with tumour differentiation and lymphatic invasion, instead of other factors like tumour size, suggesting that SPRY2 may be involved in the tumour invasion process like EMT or cell differentiation rather than proliferation." (PMID 30160357, 2018).
tumor (continued). "Here we detected the expression of SPRY family in 108 paraffin‐embedded ICCs and 20 pairs of fresh ICC tissues, and further evaluated the clinical significance of SPRY2 by analyzing the correlation between SPRY expression, tumour progression and prognosis." (PMID 30160357, 2018). "RASSF1A is a tumor suppressor that is a negative regulator in the RAS-MAPK pathway and, along with SPRY2, has reduced expression in various cancers." (PMID 22548175, 2012). "It has been shown to SHP2 promotes SPRY2 mRNA expression and inhibits its activity by dephosphorylating SPRY2 during the post‐translational phase in lens and lacrimal gland development; however, there is no such evidence in tumor cells so far." (PMID 39992860, 2025). "In addition to PTEN, miR-21-5p targets other tumor suppressors such as PDCD4 and SPRY2, further potentiating oncogenic signaling and metastatic potential." (PMID 41465544, 2025). "The reduced clonogenic growth of MDA-MB-231 herein may be attributed to the upregulation of some tumor suppressor proteins such as TSPAN6, MAPK6, SPRY2, HAUS4, stomatin (STOM) and conserved oligomeric golgi complex subunit 8 (COG8)." (PMID 38283944, 2023). "SPRY2, a mammalian SPRY orthologue, is commonly inactivated in PCa and acts as a tumor suppressor." (PMID 37845209, 2023). "In our collected tissue samples, SPRY2 expression was reduced in tumor samples than in adjacent normal samples, and its expression was negatively correlated with miR-21-5p expression." (PMID 34967265, 2022). "Among these miRNAs, miR-21 has been extensively investigated in different cancers where it was shown to target important tumor suppressors such as, for example, PTEN, SPRY2, TIMP3, PDCD4, RECK, and STAT3, and thus to behave as one of the most important oncogenic miRNAs (oncomiR) identified to date." (PMID 34638467, 2021). "The authors did not detect 5mC in tumor or control samples in a small promoter region (~248 bps) of SPRY2." (PMID 34685612, 2021). "SPRY2 specifically modulates the Ras/mitogen activated protein (MAP) kinase pathway and may function as a tumour suppressor gene, since its expression has been found to be repressed in a variety of cancers." (PMID 31664995, 2019). "All mock‐treated animals achieved maximum permitted tumour burden around 73 days post‐implantation irrespective of SPRY2 status (Fig EV2H)." (PMID 29540470, 2018). "Surprisingly, tocilizumab treatment increased the incidence of visceral metastases irrespective of SPRY2 status, despite enhanced tumour response to ADT." (PMID 29540470, 2018). "FGF1 stimulation could remarkably increase tumour invasion with normal FGFR2 expression, but the invasion of RBE or HuCCT‐1 was decreased when FGFR2 was knocked down and increased when SPRY2 was knocked down." (PMID 30160357, 2018). "This was corroborated by a later report whereby lack of Spry2 expression along with high level of ERK activation was evident in putative tumorigenic cells of KRASG12D-induced neoplasia in mouse lungs." (PMID 24744103, 2014). "Moreover, SPRY2, a family member of SPRY1, has been shown to inhibit migration of tumor cells in response to serum and several growth factors." (PMID 20813052, 2010). "In this study, pBD2 showed anti-tumor potential by upregulating the expression of PTEN and downregulating the expression of SPRY2 and PLAU, and pBD2 was also shown to promote cell proliferation by upregulating the expression of CDC25A, E2F2, and PTGS2, which perhaps might lead to tumorigenesis." (PMID 36077151, 2022). "We describe changes in biological pathways across the normal to tumor spectrum and show that fibroblast growth factor (FGF) ligands are overexpressed in NPC tumors, while negative regulators of FGF signaling, including SPRY1, SPRY2, and LGALS3, are down-regulated early in carcinogenesis." (PMID 35394843, 2022).
tumor (continued). "The identification of this unique molecular interaction between SPRY2 and MET that functions to regulate the oncogenic properties of RMS raises the possibility of leveraging it for future therapeutic interventions in RMS and other tumor types where MET is aberrantly activated." (PMID 29445192, 2018). "The amplification of the SPRY2 gene in lymph node negative tumors may play an important role by inhibiting the tumor growth and invasion function of FGF and therefore could be a potential therapeutic target." (PMID 22363777, 2012). "Re-establishing feedback inhibition in Sprouty-low tumours may therefore be an effective strategy for combinatorial therapy with trastuzumab, and raises the possibility that in some HER2 overexpressing tumours, high expression of Spry2 may be a marker of response to trastuzumab." (PMID 21909357, 2011). "Sprouty2 (SPRY2) was downregulated in 31 HCC patients compared with their matched non-tumor tissues, indicating its critical tumor suppressor effects through the Ras/Raf/MEK/ERK signaling pathway." (PMID 38816668, 2024). "More importantly, it has been shown that SPRY2 may further function as a negative-feedback regulator of MEK/ERK signaling and exert its inhibitory role in tumor progression." (PMID 37845209, 2023). "However, non-tumor lung expression of miR-21, PTEN, MARCKs, TPM-1, PDCD4, and SPRY-2 did not significantly differ between LC-COPD and LC patients." (PMID 29371906, 2018).
cancer (57 papers, 2011 to 2025). A tumor composed of atypical neoplastic, often pleomorphic cells that invade other tissues. "SPRY2 inhibits cell proliferation by acting as a feedback inhibitor of the RAS-MAPK pathway downstream of FGF/FGFR, and loss of SPRY2 expression was shown to promote cancer-associated fibroblast activation and BC progression." (PMID 40705465, 2025). "Specifically, SPRY2 has been implicated in regulating key pathways involved in cancer cell growth, migration, and invasion." (PMID 37445965, 2023). "Indicative of cancer cachexia, mice harbouring SPRY2‐deficient CRPC showed significant loss of epididymal adipose tissue." (PMID 29540470, 2018). "Our work highlights the importance of HER2 signalling in mediating progression of SPRY2‐deficient cancer to CRPC." (PMID 29540470, 2018). "Loss of SPRY2 may represent one such clinically relevant lesion, as patients with SPRY2‐deficient cancers show accelerated progression to CRPC with poor overall survival." (PMID 29540470, 2018). "This may be a supplement to existing controversy of SPRY2 in cancer and help reveal more underlying function of SPRY2." (PMID 28002800, 2017). "Focusing on the mRNA expression in the stromal fibroblasts, we found that Spry2 and Spry4 are both greatly downregulated, but curiously, Spry1 is upregulated in the cancer fibroblasts." (PMID 38600092, 2024). "Consistent with these RTK-dependent activities of Spry2, its behavior in cancer shows opposite effects." (PMID 37045830, 2023). "Spry2 is a molecular modulator of tyrosine kinase receptor signaling pathways that has cancer-type-specific effects." (PMID 37045830, 2023). "Some of these reported targets are cancer-related and are associated with carcinogenesis (such as SPRY2, SKY and SRSF3), cancer prognosis (such as CNOT6, RECK and GID4) or cancer cell plasticity (such as RMND5A)." (PMID 33804639, 2021). "Recent years, researchers had further recognized that SPRY2 had a great capacity in regulating cell proliferation, survival, migration, and angiogenesis, thus became a hotspot in cancer progression." (PMID 30464168, 2018). "Since regulation of MET in RMS is largely unexplored and reports indicate that SPRY2 can alter MET signaling in cancers, we carefully analyzed MET, SPRY2 and their role in RMS, using representative RMS cell lines." (PMID 29445192, 2018). "Previous research has shown that the levels of Spry1 and Spry2 are decreased in cancers of the breast, lung, liver, and prostate correlating to poor patient prognosis." (PMID 28196140, 2017). "Because Spry2 levels are reduced in some forms of cancer, the regulation of Spry2 in cancer has been investigated." (PMID 28196140, 2017). "We demonstrated that SPRY2 suppression alters cancer cell morphology from fibroblastoid to epithelial type and decreases cell migration with concomitant increase in E-cadherin expression and reduction in EMT-inducing transcription factors." (PMID 26434583, 2016). "SPRY2 downregulation significantly increased miR-194-5p levels, altered cancer cell morphology and decreased cell migration and invasion." (PMID 26434583, 2016). "As a negative regulator of receptor tyrosine kinase-mediated signaling, Spry2 has been found to play a role in various cancers." (PMID 25663918, 2015). "We surveyed Spry2 expression in an existing microarray expression database, in which gene expression of normal or cancer epithelium was compared with that of the distal stroma of 5-week-old virgin female mice." (PMID 24718286, 2014). "A negative correlation was also evident between the expression levels of Spry2 and the microRNA miR-21, an indicator of poor survival and poor response to adjuvant chemotherapy in cancer patients." (PMID 24744103, 2014). "To validate the data from microarray, we used qPCR and examined Spry2 expression in hyperplasia and carcinoma from the PyMT model when compared with that in the normal epithelium." (PMID 24718286, 2014).
cancer (continued). "We found that Spry2 RNA expression in hyperplasia and carcinoma was 77% and 22%, respectively, of that in the normal epithelium." (PMID 24718286, 2014). "Taken together, while both Spry1 and Spry2 were moderately expressed in the normal ovarian cells employed as the control, alterations in the expression of Spry1 and/or Spry2 were found across all cancer cells studied." (PMID 23251157, 2012). "Spry2 was easily identified in all cell lines, with cancer cells expressing it in a more prominent way." (PMID 23251157, 2012). "Therefore, we mined the database and confirmed that expression of both Spry2 and Spry4 is downregulated, while Spry1 is upregulated in the cancer fibroblasts of the 4T1 model, similar to that in the human cancer." (PMID 38600092, 2024). "Overexpression of SPRY2 in several types of cancer inhibits their growth and progression." (PMID 38283944, 2023). "Spry2 expression is distinctly altered in various cancer types." (PMID 37045830, 2023). "Remarkably, no protein-coding mutation for SPRY2 has been reported or linked to any forms of cancer for that matter, including CRC." (PMID 34685612, 2021). "Multiple reports in different cancer types indicate that SPRY2 regulates MET levels." (PMID 29445192, 2018). "Indeed in cancers of the liver, lung, prostate and breast, Spry2 protein levels are markedly decreased correlating with poor patient prognosis and shorter survival." (PMID 28196140, 2017). "In the present study, increased miR-194 expression in SPRY2-downregulated cells may indicate increased cancer cell differentiation." (PMID 26434583, 2016). "Interestingly, Spry2 expression was greatly reduced in both hyperplastic adenoma and advanced carcinoma." (PMID 24718286, 2014). "Moreover, the loss of HOXA5 could promote PCa malignancy, EMT phenotype and drive cancer stemness through a previously-unreported TRAF7/HOXA5/SPRY2–MEK/ERK signaling axis." (PMID 37845209, 2023). "Likewise, the role of Spry proteins, mainly Spry1 and Spry2, in cancer has also been investigated." (PMID 28196140, 2017). "To test this hypothesis, we suppressed both SPRY1 and SPRY2 in cancer cells by siRNA method." (PMID 26434583, 2016). "Spry proteins, in particular Spry1, Spry2, and Spry4 isoforms that may have an important role in controlling growth signals, are evidently deregulated in some pathological conditions including cancer." (PMID 23251157, 2012). "In Ras/MAPK mutant cancers, a conserved gene signature that includes ETV4/5, SPRY2/4, DUSP4/6, and EPHA2/4 is a reliable biomarker of pathway activation and is associated with good clinical response to MEK inhibitor therapy." (PMID 41446112, 2025). "In LIHC cancer cell Huh7 xenografts, knockdown of METTL3 or treatment with STM2457 resulted in decreased m6A modification and up-regulated expression of DUSP5 and SPRY2, suggesting that METTL3 suppression has a repression effect on the MAPK cascades." (PMID 38012755, 2023). "HOXA5, which is identified as a novel target of TRAF7, has been demonstrated to bind directly to the SPRY2 promoter and subsequently regulate the MEK/ERK signaling pathway, thus to affect PCa proliferation, metastasis, and cancer stemness." (PMID 37845209, 2023). "Accordingly, over-expression of miR-21 in human cancers results in a decreased level of the tumor-suppressor proteins PTEN, PDCD4, SPRY2, and/or RECK, thereby promoting cell proliferation." (PMID 34066762, 2021). "Downregulation of SPRY2 is more prominent in HCC with poor prognosis, which is considered to confer an advantage to cancer cells with unrestricted ERK activity." (PMID 34204242, 2021). "Our results suggest that expression levels of SPRY2 and ETV4 are likely indicative of the sensitivity of cancer cell lines to many MAP kinase inhibitors." (PMID 33858332, 2021). "Majority of the cancer samples demonstrated upregulation of SPRY1 and SPRY2 transcripts as compared with adjacent controls." (PMID 26434583, 2016).